CD14 (CD14 molecule)
Diseases named in the same sentence as CD14 in open-access papers (continued):
Sharing a sentence is not in itself a finding about the gene and the disease.
Alzheimer disease (16 papers, 2004 to 2026). A progressive, neurodegenerative disease characterized by loss of function and death of nerve cells in several areas of the brain leading to loss of cognitive function such as memory and language. "Elevated levels of CD14 have been associated with other neurodegenerative diseases such as Alzheimer’s disease." (PMID 36428965, 2022). "We show that there is an Alzheimer’s disease-associated increase in expression of PTK2B in CD14+ monocytes (Fairfax), whole blood and peripheral blood (GTEx7 and YFS, respectively)." (PMID 33959712, 2021). "Our TWAS analyses provide evidence that expression of MS4A4A and MS4A6A in CD14+ monocytes is relevant to Alzheimer’s disease risk, although conditional analyses are unable to conclusively localise the signal to either of these genes." (PMID 33959712, 2021). "Deletion of CD14 attenuates Alzheimer’s disease pathology and polymorphism in a CD14 monocyte receptor is a genetic risk factor for Parkinson’s disease." (PMID 28792504, 2017). "Our results suggest that the immunosuppressant effects of glimepiride were mediated by the reduced expression of CD14, a molecule that acts as a receptor for LPS and neurotoxic peptides associated with prion, Alzheimer’s disease and Parkinson’s disease." (PMID 24952384, 2014). "Elevated CD14 levels in CSF from patients with Alzheimer’s disease and elevated osteopontin levels in CSF from patients with Parkinson’s disease were detected using both the screening and confirmatory assays, rendering them promising biomarker candidates." (PMID 39767701, 2024). "Increased CD14 concentration was detected in CSF of patients with Alzheimer’s disease in comparison to controls by both the proteomic screening assay and quantitative ligand-binding assays." (PMID 39767701, 2024). "Increased CD14 levels were detected in CSF samples from patients with Alzheimer’s disease in comparison to healthy controls (p = 0.0177)." (PMID 39767701, 2024). "Quantitative ligand-binding assays confirmed that CD14 levels were elevated in CSF of patients with Alzheimer’s disease (p = 0.0177), whereas osteopontin levels were increased in CSF of patients with Parkinson’s disease (p = 0.0346)." (PMID 39767701, 2024). "We detected a significant association between Alzheimer’s disease risk and an increase in expression of LACTB2 in CD14+ monocytes in both the Fairfax and in the CTS TWAS." (PMID 33959712, 2021). "After conditional analysis of the Fairfax TWAS results, we detected an association between an increase in expression of MS4A4A in naïve CD14+ monocytes and Alzheimer’s disease." (PMID 33959712, 2021). "We detected an association between changes in gene expression in both naïve and induced CD14+ monocytes and Alzheimer’s disease." (PMID 33959712, 2021). "We detected a significant association between an increase in expression of MS4A4A and MS4A6A and Alzheimer’s disease risk in both the Fairfax and in the CTS TWAS in CD14+ monocytes and the direction of effect is the same in both TWAS." (PMID 33959712, 2021). "It is shown that fibrillar amyloid β (Aβ) can directly interact with Toll-like receptor 2 (TLR2), TLR4, and CD14 to induce microglial Aβ phagocytosis at the initial stages and neuroinflammatory responses at the late stages of Alzheimer's disease." (PMID 25563673, 2014). "Next, CD14 protein expression was analyzed in plasma and CSF samples from patients with Alzheimer’s disease, Parkinson’s disease, multiple sclerosis, and amyotrophic lateral sclerosis and from healthy controls (dilution of 1:2000 for plasma samples and 1:500 for CSF samples)." (PMID 39767701, 2024). "Moreover, an elevated soluble CD14 precursor was previously found in CSF of patients with both Alzheimer’s disease and Parkinson’s disease in comparison to healthy controls." (PMID 39767701, 2024).
Alzheimer disease (continued). "We have shown an association between an increase in expression of MS4A4A and MS4A6A in naïve CD14+ monocytes and Alzheimer’s disease, whereas, after induction with in LPS-induced monocytes, a decrease in gene expression of MS4A4E is associated with Alzheimer’s disease." (PMID 33959712, 2021). "We have shown an association between changes in gene expression in naïve and induced CD14+ monocytes and Alzheimer’s disease in seven genes in known Alzheimer’s disease loci, three of which (PVR, PTK2B and MS4A6E) replicated in TWAS using independent summary statistics." (PMID 33959712, 2021). "Upregulated CD14 levels have been demonstrated in brain tissues of murine models of Alzheimer’s disease compared to control animals, and CD14-positive cells have been detected around amyloid-β plaques in post mortem brains from patients with Alzheimer’s disease." (PMID 39767701, 2024). "In both human brains and animal models of Alzheimer's disease, there is an upregulation of TLR2, TLR4, and CD14 expression." (PMID 38698886, 2024). "* Alzheimer's disease (AD): increased expression of TLR2, TLR4, and CD14 has been observed in human brains and animal models of AD." (PMID 38698886, 2024). "The previous study reported that CD14 and TLR2 were upregulated in animal models of various neurodegenerative diseases, including Alzheimer’s disease (AD), Parkinson’s disease (PD), and ALS." (PMID 27812125, 2016).
colon cancer (16 papers, 2012 to 2024). "High CD14 expression showed poorer prognosis than low CD14 expression in colon cancer as expectedly, because TAMC was demonstrated to be conditionally involved in cancer promotion." (PMID 38557819, 2024). "Previous study found increased number of CD14+ S100A9high myeloid cells in the peripheral blood of colon cancer patients compared to healthy individuals." (PMID 37347110, 2023). "Significant alteration was noted for the expression pattern of CD14 and CD11b in the DCs of patients with colon cancer." (PMID 30115896, 2018). "In the liver metastatic lesions of human colon cancer, on the other hand, only a small fraction (~10 %) of CD14+ monocytes expressed CCR1 by immunohistochemistry, whereas most of the CD15+ myeloid cells with mononuclear morphology expressed CCR1." (PMID 25326065, 2014). "Human CD14+ monocytes were co-cultured with treated colon cancer cells." (PMID 29368606, 2018). "The present data indicate that CD14+ monocytes generated from BM stem cells of colon cancer patients also show substantial cytotoxicity, which was rather associated (nonsignificantly) with CD14++CD16+ subset." (PMID 23180014, 2013). "Interestingly, PBMC incubation with the supernatant of the metastatic colon cancer line SW620 resulted in a moderate rise to 37% intermediate monocytes among CD14++ cells after 24 h." (PMID 22973451, 2012). "Using CD14 as a marker for PMN‐MDSCs in tumor‐bearing mice, we showed that PMN‐MDSCs also accumulated in SKAP1‐overexpressing colon tumors." (PMID 39269257, 2024). "To assess the value of these findings, we next analyzed the expression of perforin and GzmB in M-MDSCs (CD11b+CD33+CD14+HLA-DRlow) and PMN-MDSCs (CD11b+CD33+CD15+) of colon cancer patients and healthy donors." (PMID 31212684, 2019). "In colon cancer patients, high percentage of CD14+CD16- and CD14-CD16+ monocytes expressing CD163 was not changed after surgery." (PMID 36733385, 2022). "In both human colon cancer cell line HCT116‐ and CD14‐positive monocytes, we observed robust ChIP‐seq signals and peaks of H3K4me3 and H3K79me2, but not H3K36me3 on the promoter of FOXM1, suggesting that FOXM1 could be modulated through H3K4me3 and H3K79me2 modification across different cell types." (PMID 30628173, 2019). "In particular, non-classical CD14+CD15+ MDSC have been described in lung and colon cancer." (PMID 36189320, 2022).
multiple sclerosis (16 papers, 2009 to 2026). A progressive autoimmune disorder affecting the central nervous system resulting in demyelination. "Patients with multiple sclerosis showed an age-related shift in monocyte subsets, marked by increased CD14+CD16+ cells [rSP = 0.670, (95% CI: 0.44–0.81), P = 0.0029]." (PMID 41221125, 2025). "A link between high C-lectin expression in CD14+ cells and autoimmunity has been shown in the clinical setting and experimentally for RA and multiple sclerosis." (PMID 37662900, 2023). "Similar to our results, lower amounts of CD14++ monocytes have been described in patients with multiple sclerosis (MS) and juvenile idiopathic arthritis (JIA) with enthesitis." (PMID 32164729, 2020). "In multiple sclerosis patients it has been shown that microRNA-155 is upregulated in CD14+ monocytes and in microglia of multiple sclerosis patients compared to healthy controls." (PMID 32351507, 2020). "However, in experimental models of multiple sclerosis, fenofibrate reduced expression of IL-2, IL-6 and key Toll-like receptor signaling components (including CD14), thereby decreasing microglial activation and pro-inflammatory mediator secretion." (PMID 41009625, 2025). "For instance, in a mouse model of multiple sclerosis, TGF-β and GM-CSF secreted by the BBB have been shown to induce the differentiation of CD14+ BBB-bound monocytes towards CD83+CD209+ DCs." (PMID 36495563, 2023). "Expression of Syncytin-1 outside the placenta has been reported, capable of activating a pro-inflammatory and autoimmune cascade through receptors CD14 and TLR4 (Toll-Like Receptor 4) on antigen-presenting cells, and also of triggering dysregulation of T-lymphocytes in multiple sclerosis (MS)." (PMID 24098463, 2013).
gout (15 papers, 2015 to 2025). A condition characterized by painful swelling of the joints, which is caused by deposition of urate crystals. "Our study has unveiled significant insights into the cellular mechanisms underlying pediatric gout, particularly highlighting the roles of CD14+ monocytes and DN T cells." (PMID 40370447, 2025). "In keeping with previous study, our result pinpointed that CD14 was also linked to the development of gout inflammation." (PMID 31312662, 2019). "IL1B rs1143623 and CD14 rs2569190 were associated with gout in a study of European and New Zealand Polynesian populations." (PMID 30123371, 2018). "Previous studies have identified polymorphisms in the NALP3 inflammasome, TLR-4, CARD8, IL-1β, IL-18, and CD14 genes to be associated with gout." (PMID 29023487, 2017). "Although the statistical significance was not reached (p = 0.064), the incubation of synovial fluid cells from gout patients in matched synovial fluids caused the migration of CD14+ monocytes/macrophages toward the fluid." (PMID 29056937, 2017). "Variants rs2043211 (CARD8), rs1143623 (IL1B) and rs2569190 (CD14), which were associated with gout, are functional variations in genes directly involved in the NLRP3 signaling pathway, and as such are likely to represent genuine disease-susceptibility loci." (PMID 26462562, 2015). "In addition, it is worth noting that the decreased CD14 in the gout patients might be implicated in the process of resolution of inflammation in gout." (PMID 31312662, 2019). "The significant differences in gene expression profiles between CD14+ monocytes and DN T cells in pediatric gout patients compared to healthy controls highlight the complexity of the immune response in this disease." (PMID 40370447, 2025). "In this study, we found that the involvement of CD14+ monocytes and DN T cells in pediatric gout underscores the complexity of the immune response in this disease." (PMID 40370447, 2025). "In conclusion, our study provides novel insights into the cellular mechanisms of pediatric gout, highlighting the importance of CD14+ monocytes and DN T cells in the disease process." (PMID 40370447, 2025). "Specifically, the patient group demonstrated a markedly elevated presence of CD14+ monocytes, suggesting a pivotal role for these cells in the pathogenesis of gout in children." (PMID 40370447, 2025). "We analyzed the causal effects of Species-Bacteroides_faecis on gout and CD16 on CD14− CD16+ monocytes." (PMID 39492788, 2024). "CD14+ monocytes in the synovial fluid from patients with gout exhibit phenotypes of anti-inflammatory as well as pro-inflammatory characteristics." (PMID 35874765, 2022). "In gout, the engagement of CD14 mediates the phagocytosis of monosodium urate crystals by macrophages and their subsequent inflammatory response, culminating in interleukin−1β production." (PMID 33919522, 2021). "Collectively, these results indicated that CD14+ macrophages in the synovial fluid of patients with gout play an important role in the removal of MSU crystal-induced NETs during gout attacks." (PMID 33741037, 2021). "Collectively, these findings indicate that CD14+ macrophages in the SFMCs of patients with gout have a capacity to engulf NETs, particularly in the presence of MSU crystals." (PMID 33741037, 2021). "After stimulation with LPS, the levels of pro- and anti-inflammatory cytokines (except TGF-β1) were significantly increased in synovial fluid CD14+ macrophages of patients with gout." (PMID 33741037, 2021). "In this study, we found that the proportion of CD14-positive PBMCs was decreased in gout patients when compared with healthy controls and the serum sCD14 level was also considerably decreased in gout patients in comparison to healthy controls." (PMID 31312662, 2019). "Although CD14 was important for the development of gout, we observed a decreased CD14 production in the gout patients." (PMID 31312662, 2019).
gout (continued). "Certainly, further studies are required to explore the specific regulation mechanism between CD14 and gout." (PMID 31312662, 2019). "Taken together, our results indicate that there is a significant increase and possible role of CD14+ monocytes/macrophages in the synovial fluid during an acute attack in patients with gout." (PMID 29056937, 2017). "In the present study, we demonstrated that the number and frequency of CD14+ monocytes/macrophages was significantly increased in the joint fluids of gout patients during an acute gout attack." (PMID 29056937, 2017). "In the present study, we also found increased amounts of CD14+ monocytes/macrophages in the synovial fluid samples of patients with acute gout attacks." (PMID 29056937, 2017). "In contrast, CD14+ cells in gout patients showed marked expression of CD163, a marker for alternative activation of macrophages (M2)." (PMID 29056937, 2017). "In conclusion, we demonstrated that the number and frequency of CD14+CD3−CD19−CD56− monocytes/macrophages was markedly increased in the synovial fluid cells of patients with gout." (PMID 29056937, 2017). "Then, we evaluated the inflammatory phenotypes of CD14+ monocytes/macrophages in patients with gout." (PMID 29056937, 2017). "CD14+ cells from gout patients produced significantly higher levels of IL-1β secretion compared to cells from RA patients." (PMID 29056937, 2017). "Taken together, these data suggest that CD14+ cells from patients with gout are infiltrated monocytes and exhibit phenotypes of anti-inflammatory as well as pro-inflammatory characteristics." (PMID 29056937, 2017). "It indicated that CD14+ cells with phenotypes of M2 in gouty arthritis have higher phagocytic activity for MSU crystals." (PMID 29056937, 2017). "Nominally significant (P < 0.05) associations with gout were detected at CARD8 rs2043211 (OR = 1.12, P = 0.007), IL1B rs1143623 (OR = 1.10, P = 0.020) and CD14 rs2569190 (OR = 1.08; P = 0.036)." (PMID 26462562, 2015). "Our study revealed a significant enrichment of CD14+ monocytes in pediatric gout patients, suggesting that these cells may be hyperactivated in response to MSU crystals." (PMID 40370447, 2025). "Notably, the gene expression landscapes of CD14+ monocytes and dnT cells were starkly different between the two groups, underscoring the heterogeneity of cellular responses in pediatric gout." (PMID 40370447, 2025). "The observed shifts in gene expression profiles within CD14+ monocytes and dnT cells provide a molecular basis for the clinical manifestations of gout in children and may guide the development of targeted immunomodulatory therapies." (PMID 40370447, 2025). "Gene set enrichment analysis (GSEA) of CD14+ monocytes from pediatric gout patients and healthy children provided novel insights into the molecular signaling pathways and mechanisms underlying pediatric gout, potentially paving the way for the development of new therapeutic strategies." (PMID 40370447, 2025). "Our findings revealed that CD14+ monocytes and DN T cells play crucial roles in pediatric gout." (PMID 40370447, 2025). "In patients with gout, CD14+ monocytes were markedly increased in the synovial fluid." (PMID 35874765, 2022). "Thus, the authors came to a conclusion that CD14+ cells of the synovial fluid from the patients with gout are infiltrated monocytes and exhibit phenotypes of anti-inflammatory as well as pro-inflammatory characteristics." (PMID 35874765, 2022). "In addition, we showed that CD14+ macrophages from the synovial fluid of patients with gout can engulf MSU crystal-induced NETs, as evidenced by NE and MPO or SYTOX Green uptake in confocal microscopy or flow cytometry, respectively." (PMID 33741037, 2021). "Besides neutrophils and CD14, purinergic signaling pathways play a synergistic role in gout resolution through the regulation of inflammatory responses." (PMID 34925366, 2021).